BRCA2 (BRCA2 DNA repair associated)
Diseases named in the same sentence as BRCA2 in open-access papers (continued):
Sharing a sentence is not in itself a finding about the gene and the disease.
breast cancer (continued). "Based on the data gathered, we propose, for the first time, that SOC therapies used in ER+ breast cancer reduce the expressions of DNA repair proteins, XRCC1, FEN1, BRCA1, BRCA2 and RAD51, caretakers in maintaining genomic integrity." (PMID 37914699, 2023). "In contrast, SLUG is a negative regulator of BRCA2 in human breast cancer via recruitment of CtBP1 and HDAC1 at E boxes in the BRCA2 promoter." (PMID 37370762, 2023). "Breast Cancer 1 gene (BRCA1) and Breast Cancer 2 gene (BRCA2) are included in the category of high penetrance genes." (PMID 37055759, 2023). "In MCF-7 cells, we also found that successful expression of BRCA1 and BRCA2 lowered expression of P-MAPK in the MAPK signaling and controlled breast cancer cell proliferation." (PMID 36631481, 2023). "In contrast, the most common type of BRCA2 breast cancer was luminal-type breast cancer, and the luminal-HER2 type was more frequent in BRCA2 than BRCA1 tumors (p < 0.001)." (PMID 36905492, 2023). "Mean ages at breast cancer diagnosis of BRCA1, BRCA2, and non‐carriers were 39.8, 46.2, and 42.0 years, respectively." (PMID 35778884, 2023). "The association of germline pathogenic variants in BRCA2 gene and triple‐negative breast cancer (BC) is uncommon." (PMID 37485802, 2023). "PRMT5 expression was moderately to strongly correlated (Pearson score ≥ 0.4) with established DDR genes such as BRCA1, BRCA2, RAD51, RAD51D, RAD51AP1, FANCA, and FANCI across 125 ovarian and breast cancer cell lines." (PMID 37861290, 2023). "In this regard, thequantitative assessment of Partner and localizer of BRCA2 (PALB2) and BRCA1Interacting Helicase 1 (BRIP1) genes expression in the breast cancer cell lineunder the treatment of Tamoxifen (TAM) was executed in this study." (PMID 39430039, 2023). "The study of 94 familial breast cancers demonstrated RAD21 overexpression in 43%, 44% and 33% of BRCA1, BRCA2 and BRCAX tumours, respectively, and expression was associated with shortened cancer-specific overall survival (Hazards Ratio 1.66, p = 0.003)." (PMID 36831687, 2023). "The binding of Rad51 then recruits and activates breast cancer genes 1 and 2 (BRCA1 and BRCA2), which allows for BRCA2-mediated invasion of the sister chromatid that acts as a template for repair." (PMID 37695845, 2023). "BRCA1 and BRCA2 had affected 3% and 5% of the study population, respectively, and were collectively altered in 6%, with co-occurrence of BRCA1/2 in 7 breast cancers." (PMID 38098088, 2023). "Among participants with family history of breast cancer, PTVs in ATM (p-value = 0.002), BRCA2 (p-value = 0.005), BRCA1 (p-value = 0.046), PALB2 (p-value = 0.039) and RAD50 (p-value = 0.044) were significantly associated with increased risk of breast cancer." (PMID 37790698, 2023). "This work is significant for Black breast cancer patients, who may require CLIA-certified genetic testing because it employs comprehensive sequencing to identify more than the three Ashkenazi Jewish founder variants in BRCA1 and BRCA2 assessed by some DTC genetic tests." (PMID 37775604, 2023). "Up to ~25% of hereditary BC can be explained by the existence of highly penetrant risk variants in the tumor suppressor genes BReast CAncer gene 1 (BRCA1) and BReast CAncer gene 2 (BRCA2)." (PMID 37627152, 2023). "Different miRNA expression profiles have been identified in healthy women, women with sporadic breast cancer and women with BRCA-mut breast cancer, and, to some degree, between BRCA1-, BRCA2- and BRCAX-related tumours." (PMID 36831687, 2023).
breast cancer (continued). "The Qatari National Center for Cancer Care and Research (NCCCR) genetic screening program uncovered 90 VUS in 78 patients with breast cancer; 29 patients with 36 BRCA1 VUS and 49 patients with 54 BRCA2 VUS." (PMID 37335020, 2023). "The most predominant cancer marker for breast cancer identification as well as monitoring is cancer antigen 15-3; additional biomarkers that are related to breast cancer are CA 27.29, BRCA1, BRCA2 and (carcinoembryonic antigen) CEA." (PMID 36979610, 2023). "Breast Cancer 1 (BRCA1) and Breast Cancer 2 (BRCA2) pathways are observed in over 18% of women with High-Grade Serous Ovarian Cancer (HGSOC)." (PMID 37511995, 2023). "Tumor tissue derived organoids and snap frozen tissues were analyzed for BRCA1, BRCA2, ER, PR and HER2 in breast cancer, Tal2, EGF, ILF3, UBI2I, BRCA1 and BRCA2 in ovarian cancer." (PMID 37479967, 2023). "Breast cancer genes 1 and 2 (BRCA1 and BRCA2) are important players in mammary tumor development in both humans and canines." (PMID 37835752, 2023). "Using simulated case-control datasets, we show that the case-control LR method using age-specific breast cancer ORs from high-penetrance genes (e.g., BRCA1 and BRCA2) outperforms other OR analysis methods." (PMID 38725546, 2023). "Breast cancer (BC) tumorigenesis is driven by various genes, among which are such classical tumor suppressors as BRCA1 and BRCA2." (PMID 37628606, 2023). "Pluripotency markers OCT4, SOX2 with cancer markers BRCA1, BRCA2, ER, PR and HER2 in breast cancer iPSCs; Tal2, EGF, ILF3, UBI2I, BRCA1 and BRCA2 in ovarian cancer iPSCs were analyzed." (PMID 37479967, 2023). "(LCS=357) indicated that breast cancer and contralateral breast cancer are more likely for BRCA1 and BRCA2 carriers through a prospective study." (PMID 37476378, 2023). "It was reported that expression of BRCA1 and BRCA2, both let-7a targets, was down-regulated after delivery of magnetic core–shell nanoparticle (MCNP)/let-7a constructs to breast cancer cells." (PMID 35328651, 2022). "The cumulative risks to age 80 years ranged from 0.4% for male breast cancer to approximately 2.5% for pancreatic cancer for BRCA1 carriers and from approximately 2.5% for pancreatic cancer to 27% for prostate cancer for BRCA2 carriers." (PMID 35077220, 2022). "BRCAness phenotype in breast cancer has been shown to be highly correlated with the response to platinum-based chemotherapy and PARP inhibitors in BRCA1 and BRCA2 germline wild-type triple negative breast cancer (TNBC)." (PMID 35855837, 2022). "This study confirmed previous known patterns, including that ER-/PR- breast cancers are more often seen in BRCA1 PV carriers, in younger females, whereas ER + /PR + breast cancers are more often seen in BRCA2 PV carriers." (PMID 35135604, 2022). "The two familial breast cancer (BC) genes, Breast Cancer gene 1 (BRCA1) and Breast Cancer gene 2 (BRCA2), are highly penetrant and contribute to various cellular events ranging from the response to DNA damage to control of the cell cycle and apoptosis." (PMID 35464868, 2022). "Breast cancer patients enrolled under the Malaysian Breast Cancer Genetic Study between October 2002 and February 2018 were tested for BRCA1, BRCA2 and PALB2 genes." (PMID 35167615, 2022). "However, BC onset can be also caused by inherited or acquired mutations in specific genes, such as BRCA1 and BRCA2 (breast cancer gene 1 and 2)." (PMID 36358854, 2022). "The absolute risks to age 80 years ranged from 0.4% for male breast cancer to approximately 2.5% for pancreatic cancer for BRCA1 carriers and from approximately 2.5% for pancreatic cancer to 27% for prostate cancer for BRCA2 carriers." (PMID 35077220, 2022).
breast cancer (continued). "In this cross-sectional population-based study of 8,162 breast cancer patients, 323 (4.0%) had germline BRCA1 or BRCA2 PVs." (PMID 35143328, 2022). "We designed a rapid, digital pathway, supported by a genetics specialist hotline, for delivery of germline testing of BRCA1/BRCA2/PALB2 (BRCA-testing), integrated into routine UK NHS breast cancer care." (PMID 35868849, 2022). "Breast cancer genes BRCA1 and BRCA2 are tumor suppressor genes that function in DNA double-strand break repair in the homologous recombination pathway." (PMID 36439508, 2022). "Breast cancer 1 (BRCA1) and breast cancer 2 (BRCA2) tumour‐suppressor genes have been identified as two significant susceptibility genes in breast cancer, with mutations in the BRCA1 and BRCA2 genes involved at least 30% of hereditary breast cancer cases." (PMID 35762299, 2022). "The risks of developing male breast cancer compared with the general population have been estimated to be 15- to 18-fold higher for BRCA1 and 80-fold higher for BRCA2 carriers." (PMID 34320204, 2022). "For example, less than 25% of breast cancer inheritance is due to known high-penetrance genes (including BRCA1 and BRCA2)." (PMID 36171609, 2022). "Furthermore, another group of researchers using DHPLC analysis of 210 breast cancer families (129 families have no mutations in BRCA1 or BRCA2) of Australian ethnicity have identified a set of nine coding mutations of BARD1 including two novel variants (Thr598Ile and Ile692Thr)." (PMID 35650591, 2022). "The 10-year risks of developing breast cancer at 50 years were 0.8% at the 5th and 2.0% at the 95th PRSER+ distribution percentiles for BRCA2 carriers." (PMID 34320204, 2022). "Survivin has been shown to downregulate members of the HR pathway such as BRCA2 and RAD51 in breast cancer." (PMID 35563522, 2022). "Breast cancer 1 (BRCA1) and breast cancer 2 (BRCA2) play an important role in the HR repair pathway by interacting with other DNA repair proteins such as Fanconi anemia (FA) proteins, ATM, RAD51, PALB2, MRE11A, RAD50, and NBN." (PMID 35785170, 2022). "For breast cancer, several genes such as BRCA1, BRCA2, PALB2, ATM, and CHEK2 act as high- to moderate-penetrance cancer susceptibility genes." (PMID 35853889, 2022). "In summary, the Talazoparib Beyond BRCA trial is a prospective study that identifies the sensitivity of gPALB2 breast cancers to PARP inhibition and highlights the core role of PALB2 in BRCA1- and/or BRCA2-mediated HR DNA repair in human breast cancers." (PMID 36253484, 2022). "BRCA2 LGR more commonly occurred in cholangiocarcinoma (0.47%, 2/425), breast cancer (0.28%, 5/1788), and prostate cancer (0.18%, 2/1083)." (PMID 36147908, 2022). "Of the 14 patients with BRCA2 LGR, 5 (5/14, 35.7%) had breast cancers, and two had ovarian cancers (2/14, 14.3%)." (PMID 36147908, 2022).
breast cancer (continued). "The ability of PRSER+ to discriminate between controls and breast cancer cases was estimated as an AUC of 0.60 (95% CI = 0.51 to 0.69) for BRCA1 and 0.59 (95% CI = 0.55 to 0.63) for BRCA2 carriers." (PMID 34320204, 2022). "Breast cancer proteins, especially BRCA1 and BRCA2, participate in homologous recombination repair (HRR)." (PMID 35963853, 2022). "From 12,182 abstracts, 15 studies measuring gene penetrance covering 5 putative male breast cancer genes were found: ATM, BRCA1, BRCA2, CHEK2, and PALB2." (PMID 35885460, 2022). "The reversion mutations occurred only in 3 out of the 15 HRR genes: BRCA1 (3.8%), BRCA2 (3.5%) and PALB2 (2.0%) from 11 patients (6 breast cancers, 1 ovarian cancer, 1 pancreatic cancer, 1 lung cancer and 2 breast and ovarian dual cancers)." (PMID 35281878, 2022). "Our exome wide biomarkers study identified 4 SNPs [SNRK and SNRK-AS1-rs202018563G; BRCA2-rs2227943C; ZNF484-rs199826847C; and DCPS-rs1695739G] as the most significant SNPs among our patients with breast cancer compared to the healthy controls." (PMID 36268271, 2022). "Subsequently, we carried out Spearman rank correlation analysis of UBE2T and breast cancer genes (BRCA1, BRCA2)." (PMID 36088429, 2022). "We found HR mutations in approximately 15% of the patient cohort (n = 85), compared with 23% for BRCA2, 13% for GATA3, 7% for BRCA1, and 3% for PTEN in the same breast cancer patient cohort." (PMID 36230572, 2022). "In this group, 92/116 (79.3%) women with breast cancer and a MS of ≥40 tested positive for a BRCA1/2 PV (BRCA1 (n = 67) or BRCA2 (n = 25))." (PMID 34439310, 2021). "Of those never having undergone RRBSO, a slightly higher proportion of controls had breast cancer (BRCA1 60.1%, BRCA2 60.4%) and chemotherapy (51.4%/45.4%)." (PMID 33152107, 2021). "BRCA1 and BRCA2 genes had highest frequency of PVs among patients with ovarian cancer (5.4% in BRCA1 and 4% in BRCA2) followed by patients with breast cancer (2.1% in BRCA1 and 1.7% in BRCA2)." (PMID 34326862, 2021). "There was higher expression of IL6, MCP1, BCL2, luminal cytokeratins, MUC1, BRCA1, BRCA2, CEA and CA 15-3 in older women with primary breast cancer compared to younger women." (PMID 34165702, 2021). "BRCA-related breast cancers have distinct biological features, including a tendency for hormone receptor-negativity in BRCA1 carriers and hormone receptor positivity in BRCA2 carriers." (PMID 33579978, 2021). "In addition, women who develop breast cancer at an older age and report a strong family history of breast/ovarian cancer mainly in close relatives—first, second, or third degree—may also be BRCA1/BRCA2 mutation carriers." (PMID 34287479, 2021). "Both contralateral breast cancer and ovarian cancer occurrence were more frequent in BRCA1 than BRCA2 carriers." (PMID 34490083, 2021). "Overall 20-year survival in the cohort for all women for breast cancer specific survival was 98.8% (95% CI 98.3–99.1%) and for known BRCA1 carriers (n = 365) = 96.1% (95% CI 90.5–98.4%) and BRCA2 (n = 376) = 91.5% (95% CI 78.6–96.8%)." (PMID 34312777, 2021). "Among BRCA2 carriers, there were 34 deaths (8.0%), 1 from an occult ovarian cancer at RRBSO and 26 breast cancer deaths, 1 from melanoma, lymphoma, pancreatic, endometrial, lung and stomach cancer, plus 2 noncancer deaths." (PMID 33152107, 2021).
breast cancer (continued). "Specifically in breast cancer, AS affects major breast cancer-related proteins, such as the estrogen receptor (ER), BRCA1, and BRCA2, among others." (PMID 34439272, 2021). "The BRCA2-N372H variation weakens BRCA2 expression and BRCA2-P/CAF interaction and further reduces sensitivity to paclitaxel in breast cancer cells." (PMID 34367235, 2021). "Differences in transcriptome-wide gene expression variability between familial breast cancer groups (BRCA1, BRCA2 and BRCAx) were quantified by comparing tumour-specific measurements of variability (SD, CV and MAD)." (PMID 34287743, 2021). "Breast cancer specific survival was good for 119 BRCA1/2 carriers with 20-year survival in BRCA1:91.2% (95% CI 77.8–96.6) and 83.8% (62.6–93.5) for BRCA2." (PMID 34312777, 2021). "A study of 55 Japanese breast cancer patients from unrelated families investigated these patients for novel SNPs in BRCA1 and BRCA2." (PMID 33503928, 2021). "Of the deaths with BRCA1/2 PVs, 7/16 were unrelated to breast cancer; BRCA1-4/8 [ovarian (n = 2), carcinosarcoma uterus (n = 1), pancreatic (n = 1)], BRCA2-3/8 (ovarian, lung cancer, old-age)." (PMID 34312777, 2021). "In our study, CRRM was most commonly performed in younger breast cancer patients (p < 0.001) who, amongst BRCA1 and BRCA2 carriers, derive the greatest survival benefit." (PMID 33531640, 2021). "The BRCA1 and BRCA2 mutations are characterized by lacking an important error-free DNA repair process of homologous recombinational repair for repairing single-strand breaks; therefore, these mutations significantly increase the risks of breast cancer and ovarian cancer." (PMID 33802424, 2021). "Another French-Canadian woman with breast cancer was found to harbor PALB2 c.2323C>T and BRCA2 c.9004G>A." (PMID 34439348, 2021). "In a study analyzing 531 breast cancer patients, BRCA1-633delC was detected with relatively higher prevalence in patients with TNBC, whereas BRCA2-1466delT was found mainly in luminal B tumors." (PMID 34202525, 2021). "Breast cancer genes BRCA1 and BRCA2 play a role in DNA repair and co-localise in the nuclear foci with RAD51, a protein required for homologous recombination within a, probably common, DNA repair pathway." (PMID 34577828, 2021). "Odds ratios for breast cancer and PALB2 were similar to odds ratios for breast cancer and BRCA2, and higher than odds ratios previously reported for PALB26." (PMID 33479248, 2021). "Those genes are frequently altered in different cancers, including AKT1, EGFR, KRAS, and STK11 in lung cancer and AKT1, BRCA2, ERBB2, and PIK3CA in Breast cancer." (PMID 34906079, 2021). "In conclusion, the NCI site was suitable for cases of breast cancer except those related to (LCIS, DCIS, BRCA1, and BRCA2)." (PMID 34710987, 2021). "In this study we assessed the association of a comprehensive set of SNPs of VDR and GC genes and breast cancer prognosis in a cohort of 368 breast cancer patients with a positive family history of cancer but wild type for BRCA1 and BRCA2." (PMID 33917614, 2021).